TUG1 (taurine up-regulated 1)
Diseases named in the same sentence as TUG1 in open-access papers (continued):
Sharing a sentence is not in itself a finding about the gene and the disease.
tumor (continued). "These tumour-suppressive functions of miR-145 may also explain why inhibition of TUG1 efficiently induced apoptosis after partial neuronal differentiation." (PMID 27922002, 2016). "In this study, we found that lncRNA TUG1 was significantly upregulated in GC tissues compared with the corresponding non-tumor lung tissues and may serve as an independent predictor for overall survival in GC." (PMID 26913601, 2016). "Moreover, TUG1 downregulation correlated significantly with sex (p = 0.006), smoking status (p = 0.016), and tumor differentiation grade (p = 0.001)." (PMID 27485439, 2016). "The TUG1 level was also correlated with tumor invasion depth (P=0.002) and TNM stage (P=0.009)." (PMID 26913601, 2016). "In summary, the expression of TUG1 was significantly increased in CRC tumor tissues, suggesting that its downregulation may be a negative prognostic factor for CRC patients, and indicative of poor survival rates and a higher risk for cancer metastasis." (PMID 26856330, 2016). "qRT-PCR analysis was performed to detect the average expression of TUG1 in tumor tissues." (PMID 26913601, 2016). "Our data suggest that tumor expression of lncRNA TUG1 plays a critical role in CRC metastasis." (PMID 26856330, 2016). "qRT-PCR analysis was conducted to detect the average expression of TUG1 in tumor tissues." (PMID 24853421, 2014). "In the present study, we found that lncRNA TUG1 was significantly downregulated in NSCLC tissues compared with the corresponding non-tumor lung tissues and may serve as an independent predictor for the overall survival in NSCLC." (PMID 24853421, 2014). "Taken together, m6A‐mediated upregulation of Tug1 is closely related to tumor immunity, and it could inhibit the antitumor immune response of CD8+ T cells by promoting Pdl1 expression, and inhibiting the phagocytosis function of macrophages toward cancer cells by promoting Cd47 expression." (PMID 38981064, 2024). "Therefore, m6A‐mediated upregulation of Tug1 is closely related to tumor immunity and may serve as a novel immunotherapy strategy for clinical patients suffering from HCC." (PMID 38981064, 2024). "Moreover, lncRNA TUG1, HOTAIR, DLX6-AS1 and HOTTIP are prominently increased in OS, which are associated with tumor size, distant metastases, TNM stage, overall survival and recurrence-free survival." (PMID 38516191, 2024). "As MALAT1 and TUG1 are associated with migration, invasion, metastasis, progression, EMT, relapse-free survival, proliferation, angiogenesis, motility, apoptosis, tumor growth, and tumor size of BC, metformin can regulate these features by MALAT1 and TUG1 activities." (PMID 36849958, 2023). "Except for the function of TUG1 in Siglec-15 regulation identified in our study, other studies have demonstrated that TUG1 is an oncogene that promotes cancer development and increases tumor malignancy, including tumor cell survival, proliferation, migration, and invasion, in cancers such as HCC." (PMID 35237695, 2022). "Furthermore, TUG1 has been described to be involved in tumor-induced angiogenesis." (PMID 36173935, 2022). "Besides, TUG1 silencing decreased the tumor volume and tumor weight in contrast with sh-NC group." (PMID 34030715, 2021). "Notably, TUG1 could regulate tumor progression by acting as a competing endogenous RNA (ceRNA) of miRNAs." (PMID 31973032, 2020). "Besides, interference of TUG1 attenuated tumor growth by regulating miR-133b and CXCR4 in vivo." (PMID 32390763, 2020). "Above results indicated that TUG1 could promote tumor growth by miRNA-216b-5p/DLX2 in vivo." (PMID 31920462, 2020). "We further tested whether silencing of TUG1 could repress tumour growth and metastasis in vivo." (PMID 30911001, 2019). "Moreover, PDCD4 expression was positively correlated with TUG1 expression in ESCC tumor specimens." (PMID 30519392, 2018). "Therefore, the role of TUG1 in the development and progression of tumours is inconsistent." (PMID 29029461, 2017).
tumor (continued). "Next, to study whether miR-145 was involved in the tumor-promoting capacity of TUG1." (PMID 29371936, 2017). "The results indicated that increased lncRNA TUG1 was an independent prognostic biomarker for unfavorable OS but may not susceptible to lymph node metastasis and tumor progression in cancer patients." (PMID 28548946, 2017). "Moreover, increased TUG1 expression was correlated with HCC tumor size and BCLC stage, which suggests that TUG1 may play a key role in HCC development and progression." (PMID 26336870, 2015). "qRT-PCR and western blot analysis showed that, upon ALKBH5 silencing in tumor tissues, ALKBH5 and TUG1 were decreased, while SH3BGRL expression was upregulated (P < 0.01), suggesting that ALKBH5 silencing suppresses AML cell drug resistance to ADR in vivo." (PMID 39465506, 2025). "For example, lnc-TUG1, lnc-MMPA, lnc-MIAT, and lnc-ATB are lncRNAs whose expression levels are correlated with the state of the tumor immune microenvironment in HCC, suggesting their roles in regulating immune responses." (PMID 40352941, 2025). "LINC01133, like other lncRNAs of interest, such as HOTAIR, MALAT1, TUG1, and FOXCUT, should be at the forefront of clinical research, considering its importance both in the intratumoral context and in the tumor microenvironment." (PMID 40863724, 2025). "In summary, our results demonstrate that TUG1 regulates PD‐L1 and CD47 in HCC, which further inhibits CD8+ T cells activation and phagocytosis of macrophages, thereby regulating tumor immune escape." (PMID 38981064, 2024). "In hepatic carcinogenesis, TUG1 (lncRNA) adsorbs miR-1-3p, promoting IGF1 expression and tumor proliferation." (PMID 38191389, 2024). "Taurine upregulated gene 1 (TUG1) interacted with PRC2 complex and epigenetically silenced a number of tumor suppressor genes, including p21." (PMID 38203767, 2024). "Altogether, m6A‐mediated upregulation of Tug1 is related to a worse prognosis in HCC, and the knockdown of Tug1 inhibits tumor growth and metastasis of HCC." (PMID 38981064, 2024). "Meanwhile, TUG1 interacted with YBX1 to facilitate the upregulation of PD‐L1 and CD47 transcriptionally, which ultimately regulated tumor immune evasion." (PMID 38981064, 2024). "We first analyzed TUG1 expression in various cancers and found that TUG1 was especially highly expressed in CHOL, CESC, HNSC, LIHC, LUAD, LUSC, and STAD tumor tissues." (PMID 37813900, 2023). "High expression of TUG1 has been proved to be correlated with CRC pathogenesis including proliferative along with the migratory ability, cell viability, tumor growth, and subcutaneous tumor formation." (PMID 36333703, 2022). "Important promoters of tumour angiogenesis can serve as therapeutic targets, including MALAT1, TUG1, LNC00323-003, PVT1, and MIR503HG." (PMID 35052495, 2022). "TUG1 upregulated the expression of XBP1 by sponging miR-498 in ESCC cells, which enhanced tumor metastasis and growth." (PMID 35928868, 2022). "This suggests that TUG1 is a potential biomarker for poor prognosis in R/R AML patients treated with Ara-C, but the relationship between TUG1 and tumor cell resistance to Ara-C requires further study." (PMID 36532760, 2022). "Once a siRNA knocks down TUG1 in HCC, different mechanisms will be working to eliminate the tumor by suppressing its progression and improving the immune response." (PMID 35237695, 2022). "Thus, downregulation of TUG1 could suppress tumor growth by miR-542-3p/TRIB2 axis in vivo." (PMID 34030715, 2021). "We can conclude that the expression of TUG1 is significantly related to the tumor size, TNM stage, and tumor venous invasion." (PMID 34659578, 2021). "Recent studies have shown that lncRNAs have important functions in modulating various tumor progression in HCC, such as growth arrest-specific 5 (GAS5), nuclear-enriched autosomal transcript 1(NEAT1), and taurine upregulated gene 1 (TUG1)." (PMID 32295144, 2020).
tumor (continued). "For example, some lncRNAs, such as NOC2L-4.1, TUG1, and MALAT1, are well established to promote tumour growth, while other lncRNAs, such as ASMTL-AS1, LINC02381, and LINC02499 have been found to inhibit tumour progression." (PMID 33243205, 2020). "Patients overexpressing putative oncogenes MALAT1 and TUG1 in MIBC tissue presented prolonged survival, suggesting tumor suppressive effects of both lncRNAs." (PMID 33235218, 2020). "The tumor level of MET and p-AKT had the same trend that the lowest level of MET and p-AKT in the sh-TUG1 plus 2 Gy group." (PMID 31918742, 2020). "Transfection of cells with sh‐TUG1 and sh‐NC lentiviruses was carried out to further explore the impact of TUG1 on HCC tumor growth by injecting transformed cells to develop in vivo tumors in the mice." (PMID 34766130, 2020). "For instance, H19, HOTAIR, MALAT1, TUG1, GAS5, and CCAT1, were found to play important roles in tumor initiation and development 44-49." (PMID 32922554, 2020). "miR-144-3p acts as a tumor suppressor in ESCC, and depletion of miR-144-3p restored the effects of TUG1 suppression on radiotherapy, consequently validating its role as a regulator of radiation." (PMID 32947897, 2020). "Long non-coding RNA-CRNDE, TUG1 and OIP5-AS1 promote oncogenesis in HB, while experimental verification shows that LINC01314 acts as a tumor suppressor in HB." (PMID 31781561, 2019). "An additional study also revealed that TUG1 is upregulated in LAD cells and serum samples, and a high level of TUG1 is positively correlated with tumor size, TNM stage, lymph node metastases, and distant metastasis." (PMID 31480503, 2019). "Chromatin immunoprecipitation (ChIP) analysis revealed that TUG1 mediates epigenetic silencing of BAX promoter through EZH2 recruitment and consequent H3K27 hypermethylation, hence conferring tumor cells’ protection against apoptotic triggers." (PMID 29570632, 2018). "More specifically, 4 lncRNAs (CCAT1, CCAT2, HOTAIR, and UCA1) were upregulated, while 2 lncRNAs (MALAT1 and TUG1) and 1 circRNA (CDR1AS) were downregulated in CRC tumor tissues compared to NATs." (PMID 30195762, 2018). "Similar to TUG1, UCA1 showed an asymmetric distribution between tumor tissues, where the lncRNA is upregulated, and serum exosomes, where it is downregulated." (PMID 30195762, 2018). "Since then, emerging lncRNAs such as MALAT1, TUG1, and UCA1 had been demonstrated to be tumor markers or prognostic indicators of BC26." (PMID 29445179, 2018). "Expression of the seven lncRNAs UCA1, MALAT1, H19, GAS5, TUG1, ncRAN (SNHG16) and linc-UBC1 (BLACAT) was measured by RT-qPCR in UC tissue set 1 consisting of 106 tumor tissues and 10 benign tissues obtained from radical cystectomies." (PMID 28430799, 2017). "Knockdown of TUG1 inhibited the proliferation, motility, and invasiveness of cultured ICC cells, and decreased tumor burden in a xenograft mouse model." (PMID 29371936, 2017). "Among the 6 studies that reported lncRNAs function as tumor oncogenes and used tumor weight as the major outcome measure, 5 different lncRNAs (HOTAIR, TUG1, BCAR4, MALAT1 and FGFR3-AS1) were reported." (PMID 29245999, 2017). "We show here that TUG1 is upregulated in clinical ICC specimens, and high TUG1 expression correlates with poor survival and tumor progression." (PMID 29371936, 2017). "TUG1 has been validated by many studies that it play important roles in tumorigenesis and PTEN is a well-known tumor driver gene." (PMID 27580177, 2016). "After analyzing the expression levels of TUG1 in 120 CRC patients, the authors observed an up-regulation of the lncRNA in tumor tissue that in addition was closely correlated with the survival time of the CRC patients." (PMID 27148353, 2016). "Another example is TUG1-hsa-miR-34a- VEGFA, which is a competing triplet that involved in the KIRC tumor state." (PMID 27580177, 2016).
tumor (continued). "TUG1, upregulated by METTL3-mediated m6A, regulates PD-L1 and CD47 by sponging miR-141/miR-340 and interacting with YBX1; its knockdown inhibits tumor growth, enhances CD8+T/M1 macrophage infiltration, activates CD8+T via PD-L1, and boosts macrophage phagocytosis through CD47." (PMID 40352941, 2025). "In addition to miRNA, several lncRNAs, including HOTAIR, MALAT1, TUG1, and NEAT1, play crucial roles in regulating gene expression and significantly impact tumor progression." (PMID 40806675, 2025). "Likewise, in malignant melanoma, the sponging of the lncRNA TUG1 with miR-129-5p, miR-29c-3p, or miR-145-5p increased the expression of AEG-1, RGS1, and SOX2, respectively enhancing proliferation, tumor growth, and metastasis formation." (PMID 40282449, 2025). "Mechanistically, TUG1 acts as a miRNA sponge for miR-141 and miR-340 to regulate PD-L1 and CD47 expression and interacts with YBX1 to transcriptionally upregulate both immune checkpoint molecules, thereby modulating tumor immune escape." (PMID 41346602, 2025). "TUG1 regulates the expression of PD-L1 and CD47 by adsorbing miR-141 and miR-340, respectively, and interacts with YBX1 to promote their transcriptional upregulation, ultimately facilitating tumor immune evasion." (PMID 40352941, 2025). "Taken together, TUG1 upregulate PD‐L1 to inhibit the antitumor immune response of CD8+ T cells, and upregulates CD47 to inhibit the phagocytosis of macrophages, ultimately promoting tumor immune escape." (PMID 38981064, 2024). "For instance, tumor-suppressor miRNAs such as and miR-199b-3p, miR-129-3p, miR-490-3p, and miR-26a-5p directly repress AURKA, whereas lncRNAs like MALAT1 and TUG1 indirectly upregulate AURKA by sponging and downregulating tumor-suppressor miRNAs." (PMID 39598228, 2024). "Mechanistically, TUG1 recruited ALYREF to maintain the stabilization of enhancer of zest homolog 2 (EZH2) mRNA and expression of H3K27me3, repressing the transcription of the tumor-suppressor gene CPEB1." (PMID 40330150, 2024). "Therefore, we examined the mechanism by which TUG1 interacts with PD-L1 in HCC and evaluated its contribution to tumor immunology." (PMID 37813900, 2023). "A tumour-suppressive function has also been discovered for MEG3 and TUG1." (PMID 38203731, 2023). "The systemic delivery of ASO targeting TUG1, coupled with cRGD peptide-conjugated polymeric micelles that enable ASO accumulation within the tumor, induced GSC differentiation and potently reduced tumor growth in an intracranial xenograft mouse model." (PMID 37047365, 2023). "In addition to the tumor-promoting function of TUG1, our findings further identified SP1, which was an up-regulated gene in CRC, to serve an upstream mediator of TUG1." (PMID 35508523, 2022). "The results demonstrated that the expression of anti‐tumour lncRNAs DICER‐AS1, TUG1, GAS5 and LINC01121 was significantly increased by 50 μM resveratrol in combination with H19 knockdown, while expression of MALAT1 in cells was significantly downregulated by the combined treatment." (PMID 35166018, 2022). "Silencing of TUG1 and SCAT7 significantly reduced tumour growth." (PMID 36230680, 2022). "The purpose of the present study was to confirm the differential expression of TUG1 in HCC and to determine whether it regulates IFITM3 through miR-29a, thereby affecting tumor invasion, migration, proliferation, and apoptosis." (PMID 34659578, 2021). "MiR‐144‐3p was confirmed to be a target of TUG1 in tumour models, however, among all these studies related to oxidative damage, miR‐144‐3p was never studied as a target of TUG1." (PMID 34547172, 2021). "In addition, by examining tumor tissue using qRT-PCR and western blotting, we found that the expression of IFITM3 in tumor tissues of mice with TUG1 knockdown was significantly lower than that in the other two groups." (PMID 34659578, 2021).
tumor (continued). "It has been confirmed by immunoprecipitation that TUG1 may recruit and bind to polycomb repressive complex 2 (PRC2) to regulate gene expression involved in tumorigenesis and tumor development." (PMID 33747256, 2021). "The lung metastasis test showed that the degree of tumor metastasis and the average area of IFITM3 immune-positive lung tissue were significantly reduced after knocking down TUG1, whereas simultaneous knocking down TUG1 and miR-29a resulted in findings similar to those obtained in the control group." (PMID 34659578, 2021). "In this study, the establishment of a xenograft tumor model in nude mice using paclitaxel resistant A2780 cells with or without TUG1 silencing, confirmed that TUG1 promoted cancer progression and paclitaxel resistance in vivo by inhibiting miR-29b-3p." (PMID 34204094, 2021). "In addition, we found that TUG1 knockdown inhibited the tumorigenesis of HemECs in vivo, accompanied by miR-137 upregulation and IGFBP5 downregulation in tumor tissues." (PMID 34362467, 2021). "Patients and methods: The expression of TUG1 and miR-29a in tumor tissues and adjacent non-tumor tissues of 65 patients with HCC was detected by real-time quantitative polymerase chain reaction (RT-qPCR)." (PMID 34659578, 2021). "Our experiments with and without the use of animals revealed that blocking nude mice tumor development occurred in tandem with decreased HCC cell motility, metastasis, and proliferation associated with lncRNA TUG1 silencing." (PMID 34766130, 2020). "Furthermore, the expression of TUG1, miR-216b-5p and DLX2 in resected tumor tissues was measured, compared to the sh-NC group, TUG1 and DLX2 were decreased and miR-216b-5p was increased in the sh-TUG1 group." (PMID 31920462, 2020). "More than that, TUG1 was aberrantly aggrandized in HCC tissues, and it could promote cell growth and tumor formation by targeting KLF2." (PMID 31920462, 2020). "However, reduced tumor levels of Ki67 and lowest levels of MET and p-Akt observed in the 2 Gy radiation group depleted with si-TUG1." (PMID 32947897, 2020). "Tumor suppressive lncRNAs (GAS5, MEG3, FER1L4 and LINC00672) and oncogenic lncRNAs (CCAT2, BANCR, NEAT1, MALAT1, H19, Linc-RoR, TUG1, TDRG1 and PCGEM1) may be a few such examples." (PMID 30781521, 2019). "In the present study, we analyzed TUG1 expression levels of PCa patients in tumor and adjacent normal tissue by real-time quantitative PCR." (PMID 29967294, 2018). "Across all cancer-related lncRNAs, TUG1 was a newly identified non-protein coding RNA gene, it participates in regulating proliferation and apoptosis in a variety of tumor cells." (PMID 29029461, 2017). "RNA-FISH analysis showed that neither TUG1 nor Notch1-positive cells were observed in residual tumours in mice with TUG1-DDS treatment, whereas in mice with CTRL-DDS treatment, TUG1 and Notch1 expression was predominantly observed in the perivascular regions." (PMID 27922002, 2016). "While Tusc7 seems to act as a tumor suppressor and is reduced in severaltypes of cancer, the picture for taurine up-regulated 1 (Tug1), another p53regulated lncRNA, is not as clear." (PMID 27508057, 2016). "We determined the levels of TUG1 expression in 89 pairs of NSCLC tumor and nontumor lung tissues by using qRT-PCR." (PMID 27485439, 2016). "Additionally, noncoding RNAs such as lncRNAs (CRNDE, MIR210HG, SNHG9, TUG1) and circRNAs (CDR1) interact with miRNAs (miR-7–5p, miR-608) to modulate the expression of downstream targets such as KLF4 and FOXO6, further influencing tumor stemness and malignancy." (PMID 41393242, 2025). "While there is no direct TUG1-based treatment for WT, research indicates that it may play a role in tumor development and progression." (PMID 40722750, 2025).